SIRT6 (sirtuin 6)
Diseases named in the same sentence as SIRT6 in open-access papers (continued):
Sharing a sentence is not in itself a finding about the gene and the disease.
Cachexia (continued). "This shows that the circulating SIRT6 level is negatively correlated with cachexia development in cancer patients and suggests that SIRT6 may have a protective effect against cancer cachexia." (PMID 39971710, 2025). "Therefore, we believe that SIRT6 is a promising therapeutic target to treat a multifactorial syndrome like cachexia." (PMID 34212132, 2021). "Hence, we generated skeletal muscle‐specific SIRT6 over‐expressing mice and studied its effect in tumour‐induced cachexia." (PMID 34212132, 2021). "In addition, SIRT6 overexpression protects mice from cachexia‐related WAT and muscle wasting." (PMID 39971710, 2025). "Therefore, increasing SIRT6 activity or expression has been proposed as a potential therapeutic tool to counteract many disease states characterized by muscle cachexia, thanks to the ability of SIRT6 to influence myostatin expression and possibly act on multiple tissues." (PMID 35250605, 2022). "In LLC‐induced cachexia, tumour necrosis factor‐α receptor 2 (TNFR2) mediated the inhibition of SIRT6 on lipolytic signalling, because the difference in lipolysis between the WT and SIRT6 knockout group was almost eliminated by TNFR2 neutralizing antibody." (PMID 39971710, 2025). "In this study, we investigate the protective role of SIRT6, an important regulator of energy homeostasis and health preservation, against Lewis lung carcinoma (LLC)–induced cachexia." (PMID 39971710, 2025). "As cachexia is a multi‐organ syndrome involving not only the adipose tissue but also the brain, liver, pancreas, gut and muscle, we used a globally overexpressing SIRT6 mouse model rather than adipose tissue‐specific overexpression model." (PMID 39971710, 2025).
cholestasis (4 papers, 2020 to 2024). Impairment of the bile flow caused by obstruction within the liver, or outside the liver in the bile duct system. "Activation of sirtuin 6 (SIRT6) prevents cholestasis-associated pathological events, such as oxidative stress and mitochondrial biogenesis dysfunction, and inhibits bile acid synthesis to alleviate cholestatic liver injury." (PMID 39618181, 2024). "To investigate the role of SIRT6 in liver injury caused by cholestasis, we used mice with hepatocyte-specific deletion of Sirt6 (Sirt6Δhep) and simulated extrahepatic cholestasis by BDL surgery." (PMID 39618181, 2024). "It has been reported that SIRT6 inhibits Cyp7a1 transcription, thereby decreasing bile acid synthesis and alleviating liver injury associated with cholestasis." (PMID 39618181, 2024). "To assess the therapeutic potential of SIRT6 as a target for cholestasis, we used the SIRT6 agonist MDL801 to treat Sirt6f/f and Sirt6Δhep mice that underwent BDL." (PMID 39618181, 2024). "This function is synergistic with SIRT6 agonists, and potentially beneficial for resistance to bile toxicity and cholestasis." (PMID 39618181, 2024). "Sirt6 activation alleviates cholestatic liver damage and fibrosis in murine cholestasis models by deacetylation of ERRγ." (PMID 32701506, 2020). "In an effort to demonstrate clinical relevance, we analyzed the expression of Sirt6 and ERRγ in liver samples from patients with cholestasis." (PMID 32701506, 2020). "Sirt6 activated the PGC-1α/NRF1, NRF2 pathway by activating AMPK phosphorylation and directly deacetylating PGC-1α, which revealed Sirt6 as a promising therapeutic target in cholestasis-induced biliary epithelial cell injury." (PMID 32206298, 2020). "In patients with cholestasis, Sirt6 expression was decreased, whereas total ERRγ and acetylated ERRγ levels were increased, confirming negative regulation of ERRγ by Sirt6." (PMID 32701506, 2020). "Based on the initial finding that ERRγ coimmunoprecipitates Sirt6, we investigated the possibility of direct deacetylation of ERRγ by Sirt6 and the biological relevance of this in cholestasis." (PMID 32701506, 2020). "Hepatic expression of Sirt6 is repressed, whereas hepatic expression of ERRγ is upregulated in murine cholestasis models." (PMID 32701506, 2020). "We observed that hepatic expression of Sirt6 is repressed, whereas hepatic expression of ERRγ is upregulated in murine cholestasis models." (PMID 32701506, 2020). "Conversely, and consistent with the animal data, Sirt6 expression was decreased in patients with cholestasis." (PMID 32701506, 2020). "However, in the presence of cholestasis, Sirt6 deletion intensified liver injury, oxidative stress, mitochondrial loss and dysfunction, and hepatocyte apoptosis." (PMID 39618181, 2024). "The current study aimed to elucidate the molecular mechanism by which SIRT6 alleviates cholestasis." (PMID 39618181, 2024). "We employed active small molecules and gene knockdown techniques to investigate how SIRT6 influences cholestasis, specifically focusing on its roles in managing oxidative stress, promoting mitochondrial biogenesis, and inhibiting bile acid synthesis in mice with hepatocyte-specific Sirt6 deletion." (PMID 39618181, 2024). "However, it remains uncertain which pathway mediates the therapeutic effect of SIRT6 in reducing cholestasis." (PMID 39618181, 2024). "To investigate whether Sirt6's ability to combat oxidative stress contributes to cholestasis treatment, we used a potent antioxidant, NAC, to treat hepatic Sirt6-deficient mice that underwent BDL." (PMID 39618181, 2024). "Additionally, the knockdown of hepatic CYP7A1, which serves as a key enzyme in the classical synthesis pathway for bile acids, significantly alleviated BDL-induced cholestasis and counteracted the adverse effects of Sirt6 deletion." (PMID 39618181, 2024).
cholestasis (continued). "To identify the pathway through which SIRT6 exerts its therapeutic effects in reducing cholestasis, we used N-acetylcysteine (NAC), KEAP1-NRF2-IN-1 (KNI-1), acadesine (AICAR), or adeno-associated virus to knock down Cyp7a1 to treat hepatic Sirt6-deficient mice." (PMID 39618181, 2024). "In humans with cholestasis, lower SIRT6 levels have been reported, thus the upregulation of SIRT6 might be a potential therapeutic intervention." (PMID 33806509, 2021). "A negative association between the expression of Sirt6 and ERRγ or its acetylation was also demonstrated in liver samples from patients with cholestasis." (PMID 32701506, 2020). "The further study of Sirt6 will bring new hope for the treatment of cholestasis." (PMID 32206298, 2020). "Hepatic expression of Sirt6 is inversely correlated with ERRγ in patients with cholestasis." (PMID 32701506, 2020). "Thus, cholestasis or SIRT6 agonists, which likely interfere with the flow of bile acids into the small intestine, may reduce the population of bile acid-metabolizing bacteria but lead to an overgrowth of other harmful bacteria in the gut." (PMID 39618181, 2024). "This suggests that SIRT6 reduces bile acid synthesis by inhibiting the expression of CYP7A1, thereby alleviating cholestasis." (PMID 39618181, 2024). "Therefore, during the administration of SIRT6 agonists for cholestasis treatment, it is beneficial to moderately increase the population of bile-acid-metabolizing bacteria and maintain intestinal flora balance, as this may increase the efficacy of the agonists and lessen potential adverse effects." (PMID 39618181, 2024). "As such, identification of Sirt6 as a molecule to inhibit CYP7A1, which decreases protein level of ERRγ, can expand our understanding of BA synthesis and cholestasis." (PMID 32701506, 2020). "Overexpression of deacetylase-mutant Sirt6 (Ad-mSirt6) did not result in an improvement in liver histology and injury markers, suggesting that the deacetylase activity of Sirt6 is required for the protective function of Sirt6 against cholestasis." (PMID 32701506, 2020). "Additionally, SIRT6 inhibits the estrogen-related receptor γ (ERRγ)-induced transcription of cholesterol 7 alpha-hydroxylase (CYP7A1), a key enzyme for bile acid synthesis, through deacetylation of ERRγ, thereby potentially attenuating bile acid accumulation and cholestasis." (PMID 39618181, 2024).
diabetic retinopathy (4 papers, 2014 to 2023). "Previous studies have shown that SIRT6 can improve diabetic retinopathy by delaying cell senescence, meanwhile the down-regulation of SIRT6 expression also participates in the pathogenesis of DCM." (PMID 32903815, 2020). "In conclusion, these results suggest that Sirt6 is a critical regulator of endothelial senescence and oxidative stress-induced downregulation of Sirt6 is likely involved in the pathogenesis of diabetic retinopathy." (PMID 25162034, 2014). "According to the authors, induced by the oxidative stress, downregulation of Sirt6 may be involved in the pathogenesis of diabetic retinopathy." (PMID 26881021, 2016). "In diabetic retinopathy, increased ROS expression and the oxidative stress may induce endothelial cells senescence via downregulation of Sirt6." (PMID 26881021, 2016).
head and neck cancer (4 papers, 2019 to 2022). A primary or metastatic malignant neoplasm affecting the head and neck. "However, low SIRT6 expression has been associated with a poorer OS in head and neck cancer, urogenital cancer, and other system cancers." (PMID 35172823, 2022). "Further, low SIRT6 expression predicted worse OS in head and neck cancer (P < 0.05), urogenital cancer (P < 0.05) and other system cancer (P < 0.05)." (PMID 35172823, 2022). "Compared with normal tissues, SIRT6 mRNA expression levels in head and neck cancer were significantly decreased in five unique analyses." (PMID 35136826, 2022). "In this study, we found that ROS-induced cell death of head and neck cancer cells is initially regulated by Sirt6 and Sirt1." (PMID 33727672, 2021).
helminth infection (4 papers, 2022 to 2024). "A recent study reveals that IEC Sirt6 deletion can also cause impaired tuft cell development and type 2 immunity in response to helminth infection." (PMID 39253083, 2024). "Here, we report that IEC Sirt6 deletion leads to impaired tuft cell development and type 2 immunity in response to helminth infection, thereby resulting in compromised worm expulsion." (PMID 36057627, 2022). "Collectively, these data show that epithelial SIRT6 is sufficient to drive helminth infection-induced epithelial remodeling through modulating STAT6 activity." (PMID 36057627, 2022). "It is reasonable to postulate that SIRT6 in the intestinal progenitor cells promotes the differentiation toward tuft and goblet cells in response to helminth infection." (PMID 36057627, 2022). "Our findings demonstrate a requirement for IEC SIRT6 in regulating helminth infection-induced intestinal epithelial remodeling to orchestrate an effective anti-helminth immunity." (PMID 36057627, 2022). "Our results reveal a novel function of SIRT6 in regulating intestinal epithelial remodeling and mucosal type 2 immunity in response to helminth infection." (PMID 36057627, 2022). "In summary, the current study for the first time demonstrates that intestinal epithelial SIRT6 promotes the differentiation of tuft and goblet cell induced by helminth infection." (PMID 36057627, 2022). "In the present study, we demonstrate that epithelial SIRT6 is essential for tuft cell development and maintaining intestinal type 2 immunity in response to helminth infection." (PMID 36057627, 2022). "SIRT6 promotes helminth infection-induced tuft and goblet cell differentiation." (PMID 38135684, 2023). "To further explore whether SIRT6 regulates helminth infection-induced epithelial remodeling in an epithelial cell autonomous manner, we used an ex vivo organoid culture system that allows physiological responses of isolated intestinal epithelium to be analyzed in the absence of stromal cues." (PMID 36057627, 2022). "Sirtuin 6 (SIRT6) deletion induces SOCS3 expression, negatively regulating tyrosine phosphorylation of epithelial STAT6 and tuft cell differentiation in response to helminth infection." (PMID 37863104, 2024). "Conversely, after helminth infection, IEC SIRT6 transgenic mice exhibit enhanced epithelial remodeling process and more efficient worm clearance." (PMID 36057627, 2022). "In addition, SIRT6 can promote intestinal tuft cell development through activation of STAT6, which subsequently enhances intestinal type 2 immune responses to protect mice from helminth infection." (PMID 39253083, 2024). "However, the roles of SIRT6 in regulating intestinal secretory cell lineage development and type 2 mucosal immunity in response to helminth infections have not been studied." (PMID 36057627, 2022).
Hutchinson-Gilford progeria syndrome (4 papers, 2015 to 2022). "Studies have revealed that reduced SIRT6 activity is linked to impaired heterochromatin sustentation, which leads to a premature aging disorder called Hutchinson-Gilford progeria syndrome (HGPS) in humans." (PMID 33920726, 2021). "The dampening of the somatotropic axis has also been observed in progeroid mouse models that are associated with elevated genome instability, albeit independent of NER, including Sirt6−/− mice as well as the Zmptse24 knockout animals that model Hutchinson-Gilford Progeria Syndrome (HGPS)." (PMID 26287260, 2015).
Hypercholesterolemia (4 papers, 2016 to 2024). An increased concentration of cholesterol in the blood. "Adenoviral SIRT6 overexpression normalizes serum LDL-cholesterol levels in a high-fat diet-induced hypercholesterolemia mouse model." (PMID 36831330, 2023). "Hepatic SIRT6 overexpression improves hypercholesterolemia in db/db mice." (PMID 36831330, 2023).
hypertensive nephropathy (4 papers, 2020 to 2025). Kidney damage that results from chronically elevated blood pressure; complications include glomerular damage resulting in proteinuria and hematuria. "SIRT6 also plays a key protective role in hypertensive nephropathy by regulating protein PTM, DNA damage, cellular metabolism, and mitochondrial function." (PMID 40218970, 2025). "In the glomeruli of patients with hypertensive nephropathy, an increase in DNA DSBs is accompanied by a decrease in Sirt6 expression." (PMID 38347622, 2024). "In hypertensive nephropathy, an increase in the number of DNA double-strand breaks (DSBs) is accompanied by a decrease in Sirt6 expression." (PMID 38347622, 2024). "Sirtuins, particularly SIRT3 and SIRT6, have been shown to exert protective effects in the pathogenesis of hypertensive nephropathy through various biological functions such as antioxidative stress, anti-apoptosis, anti-fibrosis, anti-inflammation, and anti-mitochondrial injury." (PMID 40218970, 2025). "This contention is testified by the fact that Sirt6 expression is reduced in the glomeruli of patients with hypertensive nephropathy, and Sirt6-dependent NRF2-HO1 signaling pathway relieves AngII-induced podocyte apoptosis, which leads to attenuation of hypertensive nephropathy." (PMID 37497437, 2023).
ischemic stroke (4 papers, 2022 to 2025). A stroke disorder caused by obstruction of blood flow to the brain, due to thrombotic (local blood clot formation) or embolic (due to a blood clot or other material traveling from another site) event. "SIRT6 is known to exert a protective role in atherogenesis and ischemic stroke, and act against VSMC differentiation in response to the cyclic strain." (PMID 34793336, 2022). "A recent follow-up study revealed that activated SIRT6 in macrophages repressed ischemic stroke by interacting with zeste homolog 2 to balance histone acetylation and methylation." (PMID 35855341, 2022). "Therefore, how SIRT6 regulates ischemic stroke viacell types other than ECs should be further evaluated." (PMID 35855341, 2022). "In addition, VSMCs and immune cells express SIRT6, which is downregulated in the blood cells of patients with ischemic stroke." (PMID 35855341, 2022). "Additionally, endothelial Sirt6 could exert a meaningful effect in ischemic strokes by guarding blood–brain barrier (BBB) integrity." (PMID 36978961, 2023). "Endothelial SIRT6 may also function in ischemic stroke by directly regulating histone acetylation." (PMID 35855341, 2022). "Recent studies have provided a model for screening SIRT6 activators (e.g., MDL-800 and MDL-811) for treating cancer, ischemic stroke, and other aging-related diseases such as liver fibrosis." (PMID 35855341, 2022). "The novel SIRT6 activator MDL-811 ameliorated neuroinflammation and ischemic injury via the zeste homolog 2/FOXC1 axis, highlighting the value of MDL-811 for treating aging-related ischemic stroke." (PMID 35855341, 2022). "Another concern is how SIRT6 activates AKT ( via epigenetic regulation or not) and whether AKT is critically involved in SIRT6 function in ischemic stroke." (PMID 35855341, 2022).
nonalcoholic fatty liver disease (4 papers, 2020 to 2024). "We and others previously reported that hepatic deletion of Sirt6 promoted alcoholic and nonalcoholic fatty liver disease (NAFLD), nonalcoholic steatohepatitis (NASH), and fibrosis." (PMID 32701506, 2020). "Similarly, the absence of SIRT6 in mice enhanced glycolysis and triglyceride synthesis, with the consequent onset of nonalcoholic fatty liver disease (NAFLD)." (PMID 35055159, 2022).
squamous cell carcinoma (4 papers, 2015 to 2023). A carcinoma arising from squamous epithelial cells. "It was discovered that the expression of SIRT6 increases in skin keratinocytes after exposure to UVB light via AKT pathway activation, and human squamous cell carcinomas (SCCs) have increased SIRT6 expression." (PMID 38203666, 2023).
triple-negative breast carcinoma (4 papers, 2019 to 2025). An invasive breast carcinoma which is negative for expression of estrogen receptor (ER), progesterone receptor (PR), and human epidermal growth factor receptor 2 (HER2). "In another study, low expression of SIRT6 predicted poor overall survival in triple-negative breast cancer patients." (PMID 33684691, 2021). "A study has reported that inhibition of SIRT6/NF-κB by icariin can alter redox status and enhance anti-tumor immunity and thus contain the growth of triple-negative breast cancer, indicating that the immune reprogramming strategy could be performed through redox intervention." (PMID 37252189, 2023). "However, it has also been reported that icariin can up-regulate the expression of SIRT6 protein and deacetylates H3K9 on the promoter of the NF-κB target gene to induce apoptosis and inhibit tumor cell metastasis via SIRT6/NF-κB in triple-negative breast cancer." (PMID 39845013, 2025).
viral infection (4 papers, 2018 to 2025). "Nevertheless, together with our findings they support the notion that NAMPT and SIRT6 constitute yet another way by which the macrophage can limit productive viral infection." (PMID 30886604, 2019). "Taken together, these findings suggest that SIRT6 interacts with p65 in the nucleus in a viral infection-inducible manner." (PMID 29686974, 2018). "Specifically, SIRT1, SIRT2 and SIRT5 have been shown to exhibit potent pro-viral activity by facilitating the replication of a range of viral pathogens, while in certain viral infections, SIRT1, SIRT5, and SIRT6 display anti-viral properties." (PMID 40006932, 2025).
acute liver failure (3 papers, 2022 to 2024). Rapid deterioration of liver function causing encephalopathy and coagulopathy. "Our investigation has begun from an interesting observation that hepatic Sirt6 expression significantly downregulated in the livers of human and mice with acute liver failure." (PMID 38649362, 2024). "In the present study, we explored the regulatory effects and mechanisms of SIRT6 in thioacetamide (TAA)-induced mice acute liver failure (ALF) models." (PMID 35517808, 2022). "Interestingly, UBCS039 has been used to uncover the function of SIRT6 in the a mouse model of thioacetamide (TAA)-induced acute liver failure (ALF)." (PMID 37023208, 2023).